BRF1 (BRF1 general transcription factor IIIB subunit)
Description:
General activator of RNA polymerase which utilizes different TFIIIB complexes at structurally distinct promoters. The isoform 1 is involved in the transcription of tRNA, adenovirus VA1, 7SL and 5S RNA. Isoform 2 is required for transcription of the U6 promoter.
Synonyms: TFIIIB90; BRF-1; hBRF; BRF; GTF3B; TAF3B2; TAF3C; CFDS; HEL-S-76p; TAFIII90; TF3B90
Tractability: PROTAC: ubiquitination databases record sites on it.
Target class: Transcription factor
Gene: Protein-coding gene on chromosome 14 (105,209,277 to 105,315,589, reverse strand). Ensembl gene ENSG00000185024.
Subcellular location: Nucleus
Subcellular location (Human Protein Atlas): Nuclear bodies; Nucleoplasm
Pathways (Reactome):
Gene expression (Transcription): RNA Polymerase III Abortive And Retractive Initiation; RNA Polymerase III Transcription Initiation From Type 1 Promoter; RNA Polymerase III Transcription Initiation From Type 2 Promoter
Gene Ontology:
Molecular function: protein binding; RNA polymerase III general transcription initiation factor activity; RNA polymerase III type 3 promoter sequence-specific DNA binding; TBP-class protein binding
Biological process: DNA-templated transcription initiation; rRNA transcription; transcription by RNA polymerase III; transcription initiation at RNA polymerase III promoter; tRNA transcription; transcription preinitiation complex assembly
Cellular component: nucleoplasm; nucleus; transcription factor TFIIIB complex; transcription preinitiation complex
Genetic constraint (gnomAD): Loss-of-function variants: 59 observed, 79.53 expected, observed/expected ratio (o/e) 0.74, 90% interval 0.6 to 0.92. The synonymous counts are far from expectation, so gnomAD's model fits this gene poorly and the ratio says little. Missense variants: 1,050 observed, 919.92 expected, observed/expected ratio (o/e) 1.14, 90% interval 1.08 to 1.2. Synonymous variants: 491 observed, 385 expected, observed/expected ratio (o/e) 1.28, 90% interval 1.18 to 1.37.
Homologues: Orthologues: macaque BRF1 (99% identical), chimpanzee BRF1 (97% identical), dog BRF1 (90% identical), mouse Brf1 (90% identical), rat Brf1 (90% identical), guinea pig BRF1 (88% identical), pig BRF1 (82% identical), tropical clawed frog brf1 (71% identical), zebrafish brf1b (66% identical), rabbit BRF1 (56% identical), Drosophila melanogaster Brf (43% identical), Caenorhabditis elegans brf-1 (35% identical). Paralogues in human: BRF2 (12% identical), GTF2B (9% identical).
Diseases named in the same sentence as BRF1 in open-access papers:
BRF1 is named in the same sentence as 47 diseases in open-access papers, as found by Europe PMC text mining. Sharing a sentence is not in itself a finding about the gene and the disease. The quoted sentences say what the papers report.
breast carcinoma (16 papers, 2014 to 2023). "In breast cancer tissues, increased levels of BRF1 were associated with high ER (estrogen receptor) levels; ERα was then found to associate with the BRF1 promoter and increase its expression in breast cancer cell lines, and to interact with BRF1." (PMID 32611613, 2020). "These evidences support the idea that abnormal expression of Brf1 is tightly linked to cell transformation and breast cancer." (PMID 31781337, 2019). "More interestingly, our early studies have found that Tam significantly inhibits the induction of Brf1 caused by alcohol in ER+ breast cancer cells." (PMID 31781337, 2019). "It suggests that Brf1 may be a potential diagnosis biomarker and a therapeutic target of alcohol-associated breast cancer." (PMID 31781337, 2019). "The Tam-mediated alteration of Brf1 expression may play an important role in alcohol-associated ER+ breast cancer." (PMID 25400119, 2014). "It will be of huge interest for both basic science and clinical communities to investigate this mechanism of alcohol-associated breast cancer and identify whether reducing Brf1 expression and Pol III gene transcription by direct or indirect manners represses mammary tumor development." (PMID 31781337, 2019). "BRF1 is overexpressed in hepatocellular carcinoma, breast cancer, gastric cancer, prostate cancer, and lung cancer in humans." (PMID 37760246, 2023). "In breast cancer, ethanol stimulation can promote the proliferation of Brf1 and ER+, thereby enhancing their interaction, and enhance the production of tRNA by Pol III gene transcription, further promoting tumor progression." (PMID 34975491, 2021). "There is evidence that MYC amplifies transcription of RNA pol III genes when RNA pol III genes are hypomethylated in breast cancer, specifically the nc886 gene, a short noncoding RNA, which has been shown to be occupied by BRF1 and deregulated in cancer." (PMID 33176745, 2020). "The staining signals of Brf1 in most of the breast cancer cases primarily accumulate in the nucleus, while its localization in the cytoplasm is only 3.7% (8/218)." (PMID 31781337, 2019). "At the review, we primarily focus on the discussions of abnormal Brf1 expression in the cases of human breast cancer and alcohol-induced Brf1 expression in breast cancer cells." (PMID 31781337, 2019). "This feature of Brf1 in breast cancer provides a possibility to develop a new approach by inhibiting Brf1 expression for therapy of the patients of breast cancer." (PMID 31781337, 2019). "Studies have demonstrated that alcohol dramatically increases Brf1 expression in ER+ breast cancer cell lines." (PMID 31781337, 2019). "Recent studies have demonstrated that Brf1 is overexpressed in most ER+ (estrogen receptor positive) cases of breast cancer and the change in cellular levels of Brf1 reflects the therapeutic efficacy and prognosis of this disease." (PMID 31781337, 2019). "The studies report that, for the first time, 218 samples of human breast cancer have been collected to measure the levels of Brf1 expression by immunohistochemistry method." (PMID 31781337, 2019). "In the future, more and more attention should be immersed into the studies of the Brf1 inhibitor as a novel approach of breast cancer therapy." (PMID 31781337, 2019). "In this paper, we summarize the progresses regarding alcohol-caused increase in the expression of Brf1 and Pol III genes and analysis of its molecular mechanism of breast cancer." (PMID 31781337, 2019). "Brf1 is not only a therapeutic target of breast cancer but also a biomarker of prognosis of the disease." (PMID 31781337, 2019). "HAPLN3 and BRF1 have been found relevant to breast cancer in the literature and they are both found to be among the most effective genes for our classification system." (PMID 31195961, 2019).
breast carcinoma (continued). "In estrogen receptor (ER)-positive breast cancer, the interaction of estrogen receptor alpha (ERα) with Brf1 mainly regulated the transcription of the Pol III genes—particularly tRNALeu and 5S rRNA." (PMID 29743091, 2018). "In the studies, we have presented the mechanistic analysis of ER+ breast cancer and measured the levels of Brf1 expression in 218 cases of HBC for the first time." (PMID 28972307, 2017). "In addition, our study indicates that Brf1 induction is required for ethanol to increase colony formation in soft agar, which supports an idea that ethanol‐enhanced Brf1 expression may promote alcohol‐associated breast cancer development." (PMID 28972307, 2017). "We reported that alcohol increases Brf1 expression through ERα and that BRCA1 represses alcohol‐induced Brf1 expression in ER+ breast cancer lines." (PMID 28972307, 2017). "To further explore the mechanism of high Brf1 expression with a longer survival period of ER+ cases, we treated the ER+ breast cancer line MCF7 cells with ethanol, which has been classified as a carcinogen to humans." (PMID 28972307, 2017). "In this study, we perform a mechanistic analysis characterizing that Tam represses alcohol-caused induction of Brf1 and Pol III genes in ER+ breast cancer cells, resulting in decreasing the rate of cell proliferation and colony formation." (PMID 25400119, 2014). "However, tamoxifen can hold in the incident of breast cancer by containing the effects of Brf1 and ERα, also indirectly inhibits the generation of tRNA." (PMID 34975491, 2021). "This suggests that Brf1 plays a critically important role in breast cancer." (PMID 31781337, 2019). "Studies have demonstrated that Brf1 is overexpressed in ER+ cases of breast cancer." (PMID 31781337, 2019). "In contrast, ERα siRNA significantly represses Brf1 expression in ER+ breast cancer cells." (PMID 31781337, 2019). "Brf1 is overexpressed in human biopsies of liver and breast cancer cases." (PMID 31781337, 2019). "Mechanism studies demonstrate that alcohol increases Brf1 expression in ER+ breast cancer cells." (PMID 31781337, 2019). "In terms of the feature of Brf1 in breast tissue, it strongly implies that developing an inhibitor to repress Brf1 expression may reach to the therapeutic purpose of human breast cancer." (PMID 31781337, 2019). "Although alcohol significantly enhances Brf1 expression in ER+ breast cancer cells, low dose (25mM) of alcohol alone is hard to induce transformation of nontumor breast cells (MCF-10A), while the MCF-10A cells treated with EGF are able to cause colony formation in soft agar assay." (PMID 31781337, 2019). "Alcohol increases cellular levels of Brf1 in ER+ breast cancer cells." (PMID 31781337, 2019). "However, the status of Brf1 expression in patients of breast cancer has been determined until recently." (PMID 31781337, 2019). "However, the significance of Brf1 overexpression in human breast cancer (HBC) remains to be investigated." (PMID 28972307, 2017). "The ability of Tam repressing Pol III gene transcription may have important implications for the development of Pol III gene lowering medications by using possible inhibitors of c-Jun or Brf1 to improve the efficacy of Tam treatment of breast cancer." (PMID 25400119, 2014). "However, Brf1 overexpression in human cases of breast cancer is a direct evidence." (PMID 31781337, 2019). "Similarly, high BRF1 expression is a favourable prognostic marker in breast cancer." (PMID 30858608, 2019). "Subsequently, the interaction between Brf1 and ERα upregulates Pol III gene transcription to enhance the production of tRNA, ultimately leading to the development of breast cancer." (PMID 34975491, 2021). "In the ER+ breast cancer cell line, MCF-7, alcohol activates JNK1 and enhances ERα activity to elevate Brf1 expression." (PMID 31781337, 2019).
breast carcinoma (continued). "In our study, we discovered a novel mechanism demonstrating that Tam decreases Brf1 expression and Pol III gene transcription to inhibit ethanol‐promoted colony formation of breast cancer cells." (PMID 28972307, 2017). "We treated ER+ breast cancer MCF7 cells with Tam and then determined the alteration of Brf1 expression and Pol III gene transcription." (PMID 28972307, 2017). "Inhibition of ERα by its siRNA or tamoxifen reduces cellular levels of Brf1 and Pol III gene expression and decreases the rate of colony formation of breast cancer cells." (PMID 28972307, 2017). "Here, we report that Tamoxifen (Tam) inhibits the induction of Brf1 and Pol III genes in ER+ breast cancer cells." (PMID 25400119, 2014). "This implies that the alteration of c-Jun by Tam is important for alcohol-increased expression of Brf1 and Pol III genes in ER+ breast cancer cells." (PMID 25400119, 2014). "The novel findings suggest the possibility that inhibition of Brf1 expression may be a potential approach to repress alcohol-promoted cell transformation and breast cancer development and to increase the efficacy of Tam treatment in Tam-resistant cases of ER+ breast cancer." (PMID 25400119, 2014). "This indicates that Tam represses expression of Brf1 and Pol III genes, resulting in alteration of alcohol-promoted phenotypes of ER+ breast cancer cells." (PMID 25400119, 2014). "Although PIK and PKB are able to phosphorylate Brf1, our studies indicate that alcohol activates JNK1, but not JNK2, while JNK1 indeed mediates alcohol-induced Brf1 expression in both hepatocellular carcinoma and breast cancer cells." (PMID 31781337, 2019). "The other 116 cases (53.2%) of breast carcinoma include moderate, weak, or negative staining of Brf1 in the lesion tissues, which is classified as the low Brf1 expression group." (PMID 31781337, 2019). "In addition, inhibition of ERα not only reduced the expression of Brf1 and Pol III gene but also decreased the formation rate of breast cancer cell colony." (PMID 29743091, 2018). "The other one hundred and sixteen cases (53.2%) of breast carcinoma include moderate, weak, or negative staining in the lesion tissues with SI ≤ 4, which is classified as low Brf1 expression group." (PMID 28972307, 2017). "Although studies on breast cancer have been well documented, to date, there have still been no reports on the mechanism and significance of Brf1 expression in HBC." (PMID 28972307, 2017). "The expression of TFIIIB components BRF1, BRF2 and BDP1 was in tendency higher in luminal subtypes, that of most TFIIIC components (C2-C6) in Her2-overexpressing cancer, but none of these general Pol III transcription factors showed increased expression levels in basal breast cancers." (PMID 36497214, 2022). "The increase in Brf1 and Pol III genes by alcohol in ER+ breast cancer cell lines is significantly higher than those in ER- breast cancer cell lines and nontumor breast cell lines." (PMID 31781337, 2019).
hepatocellular carcinoma (8 papers, 2016 to 2024). A malignant tumor that arises from hepatocytes. "Increased levels of BRF1 were observed in hepatocellular carcinoma (HCC) tissues and were associated with poor survival." (PMID 32611613, 2020). "We have demonstrated that high expression of Brf1 in hepatocellular carcinoma cases displays short OS period." (PMID 31781337, 2019). "Brf1 knockdown increased the sensitivity of hepatoma cells to apoptosis induced by oxaliplatin." (PMID 39308682, 2024). "A recent study indicates that Brf1 is overexpressed in hepatocellular carcinoma." (PMID 28972307, 2017). "However, the significance of Brf1 expression in human HCC (hepatocellular carcinoma) cases remains to be addressed." (PMID 26701855, 2016). "Moreover, BRF1 protein may serve as a biomarker in hepatocellular carcinoma where levels of BRF1 were higher and correlated with poor survival." (PMID 30858608, 2019). "Increase in transcription of Brf1 and Pol III genes promotes tumor formation, while high Brf1 expression results in shorter survival period for the patients of hepatocellular carcinoma." (PMID 28972307, 2017). "Repressing Brf1 expression inhibits the EGF-stimulated cell transformation, whereas DEN (diethylnitrosamine), a potent chemical hepatocarcinogen, has widely been used to induce HCC (hepatocellular carcinoma) in rodents." (PMID 31781337, 2019). "Induction of Brf1 and Pol III genes by ethanol in hepatoma cells is higher than in non-tumor cells." (PMID 26701855, 2016).
cerebellofaciodental syndrome (5 papers, 2019 to 2025). "Biallelic variants in BRF1 (MIM 604902) cause the cerebellofaciodental syndrome (MIM 616202) with a similar phenotype as our patient (delayed development, intellectual disability, abnormal facial and dental findings, and cerebellar hypoplasia)." (PMID 30552426, 2019). "Additionally, Brf1 mutations have been shown to be causative for cerebellofaciodental syndrome." (PMID 35611941, 2022). "Indeed, mutations in BRF1, encoding a subunit of the transcription factor TFIIIB-β specific to Pol III type 1 and type 2, as well as some hybrid promoters, cause a cerebellar-facial-dental syndrome." (PMID 34395528, 2021). "Furthermore, RNA pol III-dependent transcription may play a role in cerebellofaciodental syndrome which is associated with mutations in the RNA pol III-specific transcription factor, Brf1." (PMID 35611941, 2022).
prostate carcinoma (5 papers, 2020 to 2023). A carcinoma that arises from epithelial cells of the prostate gland. "Consistent with our clinical observations, BRF1 overexpression in a Pten-deficient mouse (PtenΔ/ΔBRF1Tg) prostate cancer model accelerated prostate carcinogenesis and shortened survival." (PMID 31740786, 2020). "Here, we report that elevated levels of BRF1 associate with poor prognosis in human prostate cancer." (PMID 31740786, 2020). "Emerging evidence indicates that Brf1 expression is elevated in the cases of human liver, breast, gastric, and prostate cancers." (PMID 33995823, 2021). "In vitro studies in human prostate cancer cell lines demonstrated that transient overexpression of BRF1 increased cell proliferation whereas the transient downregulation of BRF1 reduced proliferation and mediated cell cycle arrest." (PMID 31740786, 2020). "Recent studies of ours and others indicate that Brf1 overexpression is founded in hepatocyte carcinoma (HCC), breast cancer, gastric carcinoma, and prostate cancer." (PMID 33995823, 2021).
colorectal cancer (4 papers, 2019 to 2022). A primary or metastatic malignant neoplasm that affects the colon or rectum. "In another study, heterozygous mutations in BRF1 were observed in several patients with familial colorectal cancer." (PMID 32611613, 2020). "Indeed, the oncogenic potential of BRF1 has recently been questioned with loss-of-function mutations in BRF1 potentially actually responsible for some heritable colorectal cancers." (PMID 30858608, 2019). "These mutations reduced protein levels as determined by expression of the mutants in a colorectal cancer cell line or led to nonfunctional proteins as determined by the inability of yeast cells carrying corresponding mutations in yeast BRF1 to grow." (PMID 32611613, 2020).